ZNF729 (zinc finger protein 729)
Description:
May be involved in transcriptional regulation.
Tractability: PROTAC: ubiquitination databases record sites on it.
Gene: Protein-coding gene on chromosome 19 (22,286,441 to 22,317,176, forward strand). Ensembl gene ENSG00000196350.
Subcellular location: Nucleus
Pathways (Reactome):
Gene expression (Transcription): Generic Transcription Pathway
Gene Ontology:
Molecular function: transcription cis-regulatory region binding; DNA-binding transcription repressor activity, RNA polymerase II-specific
Biological process: regulation of transcription by RNA polymerase II; negative regulation of transcription by RNA polymerase II; regulation of DNA-templated transcription
Cellular component: nucleus
Genetic constraint (gnomAD): Loss-of-function variants: 16 observed, 13.62 expected, observed/expected ratio (o/e) 1.18, 90% interval 0.79 to 1.74. The upper end of that interval is the gene's LOEUF score, 1.74, which puts it in group 6 of 6, group 1 being the genes least tolerant of losing a copy. Missense variants: 1,540 observed, 1,394 expected, observed/expected ratio (o/e) 1.1, 90% interval 1.06 to 1.15. Synonymous variants: 492 observed, 451.92 expected, observed/expected ratio (o/e) 1.09, 90% interval 1.01 to 1.17.
Homologues: Orthologues: chimpanzee ZNF729 (93% identical), zebrafish znf646 (14% identical), zebrafish si:dkey-89b17.4 (14% identical), Drosophila melanogaster zf30C (14% identical), zebrafish znf576.1 (13% identical), Drosophila melanogaster CG18011 (13% identical), Drosophila melanogaster CG6791 (12% identical), Drosophila melanogaster CG30020 (10% identical), Drosophila melanogaster hang (10% identical), Caenorhabditis elegans ztf-15 (9% identical), Drosophila melanogaster mld (9% identical), Drosophila melanogaster az2 (9% identical), and 20 more. Paralogues in human: ZNF208 (56% identical), ZNF99 (56% identical), ZNF91 (49% identical), ZNF107 (44% identical), ZNF160 (30% identical), ZNF420 (28% identical), ZNF845 (27% identical), ZNF347 (27% identical), ZNF84 (26% identical), ZNF184 (26% identical), ZNF594 (26% identical), ZNF665 (24% identical), and 24 more.
Diseases named in the same sentence as ZNF729 in open-access papers:
ZNF729 is named in the same sentence as 5 diseases in open-access papers, as found by Europe PMC text mining. Sharing a sentence is not in itself a finding about the gene and the disease. The quoted sentences say what the papers report.
schizophrenia (1 paper, 2024). A major psychotic disorder characterized by abnormalities in the perception or expression of reality. "Zinc finger protein 729 was found to be decreased in patients with schizophrenia compared to the controls." (PMID 39595828, 2024).
thymic carcinoma (1 paper, 2023). Thymic carcinoma (TC) is a type of thymic epithelial neoplasm characterized by a high malignant potential. "Compared with thymomas, thymic carcinomas (TCs) had a higher mutation frequency of MYO16 (33% vs. 3%, p = 0.024) and a lower frequency of ZNF729 mutations (0% vs. 35%, p = 0.044)." (PMID 36916520, 2023).
thymoma (1 paper, 2023). A neoplasm arising from the epithelial cells of the thymus. "Additionally, patients with TCs had a higher frequency of MYO16 mutation (33% vs. 3%, p = 0.024) and a lower frequency of ZNF729 mutation (0% vs. 35%, p = 0.044) than those with thymomas." (PMID 36916520, 2023). "Notably, TCs had a distinct mutation profile with a higher mutation frequency of MYO16 than thymomas and no ZNF729 mutations in this study." (PMID 36916520, 2023).
cancer (1 paper, 2020). A tumor composed of atypical neoplastic, often pleomorphic cells that invade other tissues. "Six of these genes have been reported to be associated with cancers, including LOC284933, BOD1L2, MIR7515, ZNF729 and ZNF479, and MKL1." (PMID 32414326, 2020).
ZNF729 also shares sentences with these, for which no sentence is quoted: soft tissue sarcoma (1 paper).